CCDC92B (coiled-coil domain containing 92B)
Gene: Protein-coding gene on chromosome 17 (2,720,801 to 2,749,652, reverse strand). Ensembl gene ENSG00000277200.
Genetic constraint (gnomAD): Loss-of-function variants: 2 observed, 4.32 expected, observed/expected ratio (o/e) 0.46, 90% interval 0.19 to 1.41. That is too few expected variants to judge how well the gene tolerates losing a copy. Missense variants: 258 observed, 285.26 expected, observed/expected ratio (o/e) 0.9, 90% interval 0.82 to 1. Synonymous variants: 114 observed, 135.22 expected, observed/expected ratio (o/e) 0.84, 90% interval 0.72 to 0.99.
Homologues: Orthologues: chimpanzee CCDC92B (99% identical), guinea pig CCDC92B (87% identical), rabbit CCDC92B (87% identical), mouse Ccdc92b (85% identical), rat Ccdc92b (85% identical), dog CCDC92B (76% identical), tropical clawed frog CCDC92B (44% identical), zebrafish ccdc92ba (44% identical), zebrafish ccdc92bb (33% identical). Paralogues in human: CCDC92 (34% identical).